TIMM23B-AGAP6 (TIMM23B-AGAP6 readthrough (NMD candidate))
Synonyms: LINC00843
Gene: Protein-coding gene on chromosome 10 (49,942,056 to 50,011,654, forward strand). Ensembl gene ENSG00000178440.
Genetic constraint (gnomAD): Loss-of-function variants: 17 observed, 18.33 expected, observed/expected ratio (o/e) 0.93, 90% interval 0.63 to 1.39. The upper end of that interval is the gene's LOEUF score, 1.39, which puts it in group 5 of 6, group 1 being the genes least tolerant of losing a copy. Missense variants: 134 observed, 162.5 expected, observed/expected ratio (o/e) 0.82, 90% interval 0.72 to 0.95. Synonymous variants: 40 observed, 48.5 expected, observed/expected ratio (o/e) 0.82, 90% interval 0.64 to 1.07.